ITGBL1 (integrin subunit beta like 1)
Synonyms: OSCP; TIED
Tractability: Antibody: UniProt places it where antibodies can reach, with high confidence; its Gene Ontology location is reachable by antibodies, with high confidence; UniProt predicts a signal peptide or a membrane-spanning region.
Gene: Protein-coding gene on chromosome 13 (101,452,593 to 101,720,856, forward strand). Ensembl gene ENSG00000198542.
Subcellular location: Secreted
Pathways (Reactome):
Gene expression (Transcription): RUNX2 regulates genes involved in cell migration
Gene Ontology:
Molecular function: integrin binding
Biological process: cell adhesion; cell adhesion mediated by integrin; cell migration; cell-cell adhesion; cell-matrix adhesion; integrin-mediated signaling pathway
Cellular component: cell surface; focal adhesion; integrin complex; plasma membrane; extracellular region
Genetic constraint (gnomAD): Loss-of-function variants: 39 observed, 46 expected, observed/expected ratio (o/e) 0.85, 90% interval 0.65 to 1.11. The upper end of that interval is the gene's LOEUF score, 1.11, which puts it in group 4 of 6, group 1 being the genes least tolerant of losing a copy. Missense variants: 527 observed, 499.56 expected, observed/expected ratio (o/e) 1.05, 90% interval 0.98 to 1.13. Synonymous variants: 169 observed, 173.53 expected, observed/expected ratio (o/e) 0.97, 90% interval 0.86 to 1.11.
Homologues: Orthologues: chimpanzee ITGBL1 (99% identical), macaque ITGBL1 (99% identical), dog ITGBL1 (93% identical), pig ITGBL1 (93% identical), guinea pig ITGBL1 (92% identical), mouse Itgbl1 (91% identical), rat Itgbl1 (90% identical), rabbit ITGBL1 (80% identical), tropical clawed frog itgbl1 (77% identical), zebrafish itgbl1 (51% identical), Caenorhabditis elegans C05D9.3 (23% identical), Drosophila melanogaster Itgbn (20% identical). Paralogues in human: ITGB3 (27% identical), ITGB1 (26% identical), ITGB6 (26% identical), ITGB5 (26% identical), ITGB2 (25% identical), ITGB7 (25% identical), ITGB4 (24% identical), ITGB8 (22% identical).
Diseases named in the same sentence as ITGBL1 in open-access papers:
ITGBL1 is named in the same sentence as 50 diseases in open-access papers, as found by Europe PMC text mining. Sharing a sentence is not in itself a finding about the gene and the disease. The quoted sentences say what the papers report.
breast carcinoma (18 papers, 2016 to 2025). "ITGBL1 has been found to be overexpressed in metastatic bone cancer and reported to mediate bone metastasis in breast cancer." (PMID 38090653, 2022). "High expression of ITGBL1 facilitated bone metastasis via inducing the TGF-β signaling pathway in breast cancer." (PMID 35596183, 2022). "ITGBL1 has been reported to promote breast cancer bone metastasis by activating the TGF-β signaling pathway." (PMID 32139701, 2020). "When a blocker of the TGF-β SMAD signaling pathway was used, all of the effects of ITGBL1 overexpression were suppressed, suggesting that the TGF-β signaling pathway mediates the role of ITGBL1 in breast cancer bone metastasis." (PMID 27571063, 2016). "Previous studies have reported that RUNX2 induces ITGBL1 expression in breast cancer and melanoma." (PMID 40287769, 2025). "Studies have shown that RUNX2 regulates ITGBL1 in breast cancer, colon cancer, and melanoma." (PMID 40287769, 2025). "Recently, studies on ITGBL1 have been increasing, and it was reported that ITGBL1 could promote bone metastasis of breast cancer through transforming growth factor (TGF)-β signaling pathway." (PMID 32211321, 2020). "In breast cancer tissues, ITGBL1 is co‐expressed with bone remodelling‐ and bone metastasis‐related genes, and it could promote the bone metastasis of breast cancer cells through activating the TGF‐β signalling pathway." (PMID 32537856, 2020). "For example, in breast cancer, RUNX2 was identified as a key transcription factor that regulates ITGBL1 expression, promoting the formation of osteomimetic breast cancers and metastasis to bone." (PMID 40287769, 2025). "From two pairs of matched breast cancer samples, we found that some of the detected CNVs contained some genes that were related to breast cancer, such as PDZK1, XRCC4, Fbxl17, ITGBL1, RORA, BAGE, AMOTL1, RAP80, PIWIL4, CSE1L, and USP18." (PMID 34262604, 2021). "Moreover, we observed a positive correlation of the mRNA levels between RUNX2 and BRGs (ITGBL1, SPARC and POSTN) in primary breast cancer tissues." (PMID 27806311, 2016).
colorectal cancer (17 papers, 2019 to 2025). A primary or metastatic malignant neoplasm that affects the colon or rectum. "The association of ITGBL1 with ECM remodeling and immune evasion has been reported in ovarian and colorectal cancers, whereas PI16 has been implicated in fibrotic diseases and the activation of tumor-associated fibroblasts." (PMID 41246350, 2025). "Colorectal cancer-derived integrin beta-like 1 (ITGBL1)-rich EVs stimulate the NF-κB signaling pathway via tumor necrosis factor (TNF) alpha-induced protein 3 (TNFAIP3) to activate fibroblasts at metastatic sites and promote cancer metastasis." (PMID 38318528, 2024). "For example, colorectal cancer (CRC)-derived sEVs are enriched in integrin beta-like 1 (ITGBL1), and when released into circulation, activate fibroblasts to promote the formation of pre-metastatic niches." (PMID 36612097, 2022). "Previous studies have demonstrated that ITGBL1 is highly expressed in some types of cancer and its overexpression promotes cancer progression in colorectal cancer, ovarian cancer, and hepatocellular carcinoma." (PMID 35584452, 2022). "Integrin beta-like 1 (ITGBL1)-enriched EVs from primary colorectal cancer cells were released to activate fibroblasts, resulting in pre-metastatic niche formation and metastatic cancer cell growth." (PMID 33578954, 2021). "On the contrary, in colorectal cancer, depletion of ITGBL1 was shown to result in decreased cellular proliferation in vitro." (PMID 32961775, 2020). "ITGBL1 has also been shown to promote the migration, invasion and adhesion of non–small‐cell lung cancer, colorectal cancer and ovarian cancer cells." (PMID 32537856, 2020). "Similarly, a study on colorectal cancer (CRC) demonstrated that ITGBL1 was co-expressed with RUNX2 and that RUNX2 regulates the ITGBL1 promoter activity, further supporting the role of RUNX2 in regulating ITGBL1 expression." (PMID 40287769, 2025). "For instance, the ITGBL1 level was elevated in colorectal carcinoma (CRC) and accelerated cell proliferation and migration." (PMID 35596183, 2022). "As observed in a colorectal cancer model, primary tumors release extracellular vesicles containing ITGBL1 (integrin beta-like 1) into the circulation, which activate fibroblasts residing in distant organs." (PMID 38473285, 2024). "However, the regulatory mechanism of ITGBL1 in colorectal cancer (CRC) remains unclear." (PMID 32211321, 2020). "Here we show that in a colorectal cancer (CRC) model, primary tumors release integrin beta-like 1 (ITGBL1)-rich extracellular vesicles (EVs) to the circulation to activate resident fibroblasts in remote organs." (PMID 32139701, 2020). "In colorectal cancer (CRC), the expression of ITGBL1 was upregulated, and the primary tumours could release ITGBL1‐rich extracellular vesicles to induce the activation of resident fibroblasts in remote organs, which promotes the metastatic cancer growth." (PMID 32537856, 2020). "However, the study on ITGBL1′s role in colorectal cancer metastasis demonstrated no such interactions." (PMID 32961775, 2020).
ovarian carcinoma (12 papers, 2017 to 2022). A malignant neoplasm originating from the surface ovarian epithelium. "For this reason, we evaluated the presence of all four ITGBL1 variants in different ovarian cancer cell lines." (PMID 32961775, 2020). "In addition, ITGBL1 caused cells to be more resistant to cisplatin and paclitaxel, major drugs used in ovarian cancer treatment." (PMID 32961775, 2020). "Our results indicate that higher expression of ITGBL1 in ovarian cancer cells is associated with the features that may worsen the clinical course of the disease." (PMID 32961775, 2020). "Our results indicate that higher expression of ITGBL1 in ovarian cancer is associated with the features that may worsen the clinical course of the disease." (PMID 32961775, 2020). "Upregulation of ITGBL1 predicted poor prognosis and promoted chemoresistance in ovarian cancer and activated fibroblasts using extracellular vesicles (EVs) via NF-κB signalling." (PMID 34409913, 2021). "As we found that ITGBL1 overexpression altered ovarian cancer cells adhesiveness, we further analyzed how ITGBL1 affects cognate cellular functions, like motility and invasiveness." (PMID 32961775, 2020). "In the present study we investigated the role of ITGBL1 in ovarian cancer cells using several in-vitro assays and global gene expression analysis." (PMID 32961775, 2020). "In ovarian cancer, ITGBL1 promotes migration and adhesion through Wnt/PCP (planar cell polarity) and FAK/SRC (focal adhesion kinase/steroid receptor coactivator) signaling pathways." (PMID 32139701, 2020). "Taken together, these results indicate that between 1 and 2.5 h after seeding ovarian cancer cells with higher ITGBL1 level have the advantage of faster spreading and creating stronger bonds with the plastic surface, either bare or coated with ECM proteins." (PMID 32961775, 2020). "In ovarian cancer, ITGBL1 was upregulated in ovarian cancer tissues compared to adjacent non‐cancer tissues, and it was positively correlated with lymph node invasion and advanced FIGO stage." (PMID 32537856, 2020). "We were the first to report in 2013 that ITGBL1 overexpression stimulates ovarian cancer cell migration rate." (PMID 32961775, 2020). "Our previous studies have indicated that increased expression of the gene coding for ITGBL1 is related to poor prognosis for ovarian cancer patients." (PMID 32961775, 2020). "Similarly, high expression of ITGBL1 facilitated cell migration and adhesion in ovarian cancer through Wnt/planar cell polarity (PCP) and focal adhesion kinase (FAK) /SRC signaling pathways." (PMID 35596183, 2022). "A poorly characterized protein called Integrin beta-like 1 (ITGBL1) may play an important role in ovarian cancer progression." (PMID 32961775, 2020). "In our current study we investigated ITGBL1 influence on ovarian cancer cells phenotype." (PMID 32961775, 2020). "We also checked whether ITGBL1 overexpression may alter cellular sensitivity toward drugs used in the standard first line chemotherapy for ovarian cancer, i.e., cisplatin and paclitaxel." (PMID 32961775, 2020). "Here, we have analyzed the influence of ITGBL1 on the phenotype of ovarian cancer (OC) cells." (PMID 32961775, 2020). "We expected that this pan-analysis could reveal general hallmarks resulting from ITGBL1 overexpression in ovarian cancer cells." (PMID 32961775, 2020). "It suggests that ITGBL1 could remain under transcriptional control of RUNX2 also in ovarian cancer." (PMID 32961775, 2020). "Also, currently available public algorithms like Kaplan-Meyer Plotter and CSIOVDB database, operating on considerably larger sample sets, return significant results indicating a correlation between ITGBL1 mRNA expression level in the tumor, as well as the survival of ovarian cancer patients." (PMID 32961775, 2020).
ovarian carcinoma (continued). "Studies showed that ITGBL1 could promote the invasion of ovarian cancer cell through Wnt/planar cell polarity (PCP) signaling and focal adhesion kinase (FAK)/Src pathway, and high expression of ITGBL1 was related to the poor prognosis and drug resistance of ovarian cancer." (PMID 32211321, 2020). "In taxol-resistant ovarian cancer cells, NEB along with DCDC2, ANKRD18B, ALDH1A1, and ITGBL1 were overexpressed suggesting the involvement of these AR-related genes in taxol resistance." (PMID 35975176, 2022). "In the case of ovaries, HPA showed very weak ITGBL1 staining in follicle cells, no staining in stromal cells, variable staining in ovarian cancer samples (from weak to absent) and weak in EFO21 ovarian cancer cell line." (PMID 32961775, 2020). "This is an opposite effect than observed in ovarian cancer cells, which is confusing since in both cancers (prostate and ovarian) ITGBL1 is proposed as a negative prognostic factor." (PMID 32961775, 2020). "We analyzed the influence of ITGBL1 on ovarian cancer cell proliferation rates and cell cycles, but we did not notice any changes." (PMID 32961775, 2020). "Later, since 2015, there have arisen a dozen or so reports concerning the ITGBL1 role in several human diseases, e.g., breast cancer, non-small cell lung cancer (NSCLC), HBV-related liver pathologies, pulmonary fibrosis, osteoarthritis, colorectal, gastric, prostate and ovarian cancer." (PMID 32961775, 2020). "More recently beta integrin-related protein 1 (ITGBL1), an integrin-like member of the EGF-like protein family rich in cysteine-rich repeats, was found highly expressed in ovarian cancer tissues, promoting ovarian cancer cell migration and adhesion through Wnt/PCP and FAK/Src pathways in vitro." (PMID 33266025, 2020).
melanoma (11 papers, 2021 to 2025). A malignant, usually aggressive tumor composed of atypical, neoplastic melanocytes. "For example, ITGBL1 can inhibit the tumoricidal ability of NK cells and promote the occurrence and development of melanoma." (PMID 38332530, 2024). "The integrin beta-like protein 1 (ITGBL1) is a factor highly expressed in melanoma CSCs; secreted ITGBL1 protein was found to impair NK cell cytotoxicity." (PMID 39199632, 2024). "ITGBL1 has been characterized as a secreted protein allowing melanoma cells to escape immune surveillance by inhibiting NK cell cytotoxicity." (PMID 34572799, 2021). "ITGBL1 inhibited immune cell cytotoxicity against melanoma cells by inhibiting NK cells cytotoxicity and counteracting beneficial effects of anti-PD1 treatment, both in vitro and in vivo." (PMID 33413419, 2021). "In this respect, NK cells have recently been implicated in the resistance to anti-PD1 evoked by a protein secreted by melanoma, ITGBL1." (PMID 34572799, 2021). "In conclusion, our data suggest that inhibition of ITGBL1 might improve melanoma response to immunotherapies." (PMID 33413419, 2021). "Recent studies suggested that Integrin beta-like protein 1 (ITGBL1), a secreted protein, upregulated in MITFlow melanoma cells, inhibits NK cells cytotoxicity." (PMID 35432344, 2022). "We identified Integrin beta-like protein 1 (ITGBL1), a secreted protein, upregulated in anti-PD1 resistant patients and in MITFlow melanoma cells, as the key immunomodulator." (PMID 33413419, 2021). "Additionally, in melanoma, it was shown that RUNX2 silencing led to decreased ITGBL1 expression, emphasizing the importance of RUNX2 in regulating ITGBL1 in different cancer types." (PMID 40287769, 2025). "On the other hand, it has also been reported that MITF expression in melanoma induces NK cell cytotoxicity by inhibiting integrin beta-like protein 1 (ITGBL1) expression, which is increased in MITF-low melanoma cells and in patients with resistance to anti-PD1 therapy." (PMID 38351314, 2024).
hepatocellular carcinoma (7 papers, 2020 to 2025). A malignant tumor that arises from hepatocytes. "A recent study also demonstrated that RUNX2 transcriptionally activates ITGBL1 in hepatocellular carcinoma, contributing to immune evasion in the tumor microenvironment." (PMID 40287769, 2025). "Integrin beta‐like 1 (ITGBL1) is involved in the migration and invasion of several cancers; however, its roles in the development and progression of hepatocellular carcinoma (HCC) remain largely unknown." (PMID 32537856, 2020).
liver fibrosis (7 papers, 2017 to 2025). "These genes are known to gradually increase upon NASH progression, with Gdf15 and Ccl20 encoding proinflammatory cytokines, Col1a1 and Col1a2 encoding collagen chain proteins, and Itgbl1 known for regulating liver fibrosis." (PMID 37914694, 2023). "In our previous gene expression profiling data set of HBV‐related liver fibrosis tissues, ITGBL1 was positively associated with the fibrosis stage and identified as a key regulator of fibrogenesis in patients with HBV infection." (PMID 32537856, 2020). "This study investigates the molecular mechanism underlying HBV-induced liver fibrosis, focusing on the role of RUNX2 in regulating integrin beta-like 1 (ITGBL1), a key factor in fibrogenesis." (PMID 40287769, 2025). "We demonstrated that ITGBL1 stimulates hepatic stellate cells (HSCs) to promote liver fibrosis by activating the TGF-β pathway, and we also found that serum ITGBL1 levels in CHB patients were significantly higher than those in healthy controls." (PMID 40287769, 2025). "In this study, we identified a novel regulatory pathway through which hepatitis B virus (HBV) induces liver fibrosis via the RUNX2-mediated upregulation of integrin beta-like 1 (ITGBL1), which can be blocked by Vitamin D3." (PMID 40287769, 2025). "Coincidentally, a previous study reported that ITGBL1 was a key upstream regulator of liver fibrosis via interactions with TGFβ." (PMID 35733144, 2022). "RUNX2 promotes liver fibrosis in HBV-infected patients by upregulating ITGBL1 expression." (PMID 40287769, 2025). "It has been reported that KRT17 is a downstream factor of TGF‐β1 and that ITGBL1 may stimulate liver fibrosis through regulating the TGF‐β1 signalling pathways." (PMID 32537856, 2020). "Our results collectively establish that HBV promotes fibrosis through the RUNX2-mediated upregulation of ITGBL1, highlighting potential therapeutic targets for CHB-related liver fibrosis." (PMID 40287769, 2025). "The functional roles of ITGBL1 were clarified by using in vitro experiments, which showed that ITGBL1 promotes HSC activation and liver fibrosis by upregulating TGFβ1." (PMID 28262670, 2017). "Itgbl1 affects ECM deposition and is involved in hepatitis B virus-induced liver fibrosis." (PMID 39558136, 2025).
prostate carcinoma (6 papers, 2020 to 2025). A carcinoma that arises from epithelial cells of the prostate gland. "In prostate cancer (PCa) patients, ITGBL1 was significantly upregulated and positively associated with lymph node metastasis status." (PMID 32537856, 2020). "In one study, ITGBL1 was shown to directly interact with integrins (in Ca2+ dependent manner) and to inhibit their functions in prostate cancer PC3 cells, hBMSC and chondrocytes." (PMID 32961775, 2020). "In addition, ITGBL1 promotes invasion and migration by activating NF-κB signaling pathway in prostate cancer, and the activation of NF-κB signaling pathway also promotes PC progression." (PMID 35584452, 2022). "First, they showed by co-immunoprecipitation that in the presence of Ca2+, ITGBL1 can directly interact with integrin β and inhibit its activity: depletion of ITGBL1 increased, whereas ITGBL1 overexpression reduced the amount of active integrin β in PC3 prostate cancer cells." (PMID 32961775, 2020). "The genes ITGBL1, DSC3, COL4A6, ANGPT1, ARMCX1, MICAL2, and EPHA5 have been recognized as pivotal genes that substantially affect the microenvironment of prostate cancer." (PMID 40943497, 2025). "For instance, ITGBL1 was proven to accelerate epithelial-mesenchymal transition (EMT), migration, and invasion by activating the NF-κB signaling pathway in prostate cancer." (PMID 35584452, 2022).
pulmonary fibrosis (6 papers, 2021 to 2023). Chronic progressive interstitial lung disorder characterized by the replacement of the lung tissue by connective tissue, leading to progressive dyspnea, respiratory failure, or right heart failure. "For instance, during the COVID-19 crisis, lncRNA (i.e., lncRNA idiopathic pulmonary fibrosis [ITBF]) was found at elevated levels and was associated with the integrin subunit beta like 1 (ITGBL1) gene in pulmonary fibrogenesis responsible for fibroblast differentiation and, thus, pulmonary fibrosis." (PMID 37678712, 2023). "In addition, lncITPF accelerates fibroblast-to-myofibroblast differentiation to promote pulmonary fibrosis by targeting H3 and H4 histone acetylation in the ITGBL1 promoter depending on hnRNP-L." (PMID 36386240, 2022).